COX7A1 (cytochrome c oxidase subunit 7A1)
Diseases named in the same sentence as COX7A1 in open-access papers (continued):
Sharing a sentence is not in itself a finding about the gene and the disease.
liver cirrhosis (1 paper, 2023). "To further elucidate the potential implications of IFI27 and COX7A1 in liver cirrhosis, we established a TAA-induced mouse liver cirrhosis model." (PMID 38275754, 2023). "In this study, IFI27 and COX7A1 were observed to exhibit higher expression levels within liver cirrhosis samples compared to the normal group." (PMID 38275754, 2023). "In conclusion, our findings underscore the critical role of oxidative stress-related mitochondrial genes (COX7A1 and IFI27) in liver cirrhosis development, highlighting their association with macrophage infiltration." (PMID 38275754, 2023). "Our investigation revealed increased levels of both IFI27 and COX7A1 in liver cirrhosis." (PMID 38275754, 2023). "Finally, two oxidative stress-related mitochondrial genes COX7A1 and IFI27 were selected as identifying genes associated with liver cirrhosis." (PMID 38275754, 2023). "Compared with the control samples, the expression levels of COX7A1 and IFI27 were significantly upregulated in the liver cirrhosis samples in both the merged dataset and validation dataset GSE89377." (PMID 38275754, 2023). "Collectively, these data suggest that aberrant COX7A1 and IFI27 expression impacts immune activity related to liver cirrhosis, identifying them as promising identifying genes for understanding this association." (PMID 38275754, 2023). "Therefore, these mitochondrial oxidative stress-related genes, COX7A1 and IFI27, have pivotal roles in the development of liver cirrhosis." (PMID 38275754, 2023). "Finally, COX7A1 and IFI27 emerged as identifying genes for liver cirrhosis, validated through a receiver operating characteristic (ROC) curve analysis and related experiments." (PMID 38275754, 2023). "We found that COX7A1 and IFI27 may be potential candidate identifying genes, and immune cell infiltration analysis elucidated the strong correlation of macrophages in the development of liver cirrhosis." (PMID 38275754, 2023).
prediabetes (1 paper, 2019). "Accordingly, IL-33 was directly associated with PRDM16 but not with UCP1 or COX7A1 in individuals with normoglycemia and T2D but not in those with prediabetes." (PMID 31073344, 2019). "Although IL-33 was not correlated with UCP1 or COX7A1, it was directly correlated with PR domain containing 16 (PRDM16) in individuals with normoglycemia (r = 0.5; P = 0.02; n = 20) and T2D (r = 0.38; P = 0.01; n = 43) but not in those with prediabetes." (PMID 31073344, 2019).
tumor (10 papers, 2018 to 2025). "Our findings also demonstrate that COX7A1 repression in embryonic and tumor cell lines is associated with a metabolic shift toward glycolysis reminiscent of Warburg effect observed in cancer." (PMID 29487692, 2018). "Further research is warranted to determine the extent to which highly glycolytic/OXPHOS-compromised COX7A1 deficient cells have increased regenerative ability, and the role of the phenotype in diverse aspects of tumor cell biology." (PMID 29487692, 2018). "Besides, COX7A1 is implicated in tumor metabolism and therapy." (PMID 34181336, 2021). "And through the immunohistochemical image, COX7A1 protein was mainly concentrated in the normal glandular area, and the expression was very low in the cancerous tumor glands." (PMID 38494472, 2024). "COX7A1, a key component of cytochrome oxidase, plays a crucial role in the energy metabolism of tumor cells, making it our focus of study." (PMID 38494472, 2024). "In this study, the higher the expression of COX7A1 in GC tissue, the worse the prognosis; but on the other hand, the expression of COX7A1 in tumor tissue is lower than that in normal tissue." (PMID 38494472, 2024). "Through the analysis of immunohistochemical data, we found that the expression of COX7A1 in tumor tissue was significantly lower than that in paracancerous tissue (both P < 0.001)." (PMID 38494472, 2024). "At the same time, we also reached a consistent conclusion in public data in TCGA and GSE66229 (both P < 0.001), that is, COX7A1 was significantly lower in tumor tissues than in paracancerous and normal tissues." (PMID 38494472, 2024). "It was found that the level of COX7A1 was significantly lower in the tumor tissues compared with normal lung tissues." (PMID 36418320, 2022). "Tumor infiltration immune cell analysis for COX7A1 showed that COX7A1 may affect the clinical efficacy of immunotherapy by promoting M2 macrophages differentiation and inhibiting M1 macrophages differentiation." (PMID 38494472, 2024). "Except Patient 1 (P1), the results from Patient 2 to Patient 6 (P2-P6) also showed that the expression of COX7A1 in tumor tissues was much lower than normal lung tissues in both RNA level and protein level, indicating the anti-cancer potential of COX7A1 during the process of NSCLC development." (PMID 36418320, 2022). "In addition, tumor biomarkers such as expression of NOTCH1, tumor hypoxia, and genetic variants in genes such as TGFβ1, COX7A1, and TBX5 have also been shown to be associated with prognosis in HPV-related HN cancer." (PMID 34830844, 2021). "As a result, the repression of epimorphic potential at the EFT, evidenced by the onset of COX7A1 expression, may provide an important role in tumor suppression." (PMID 29487692, 2018). "If it can relieve the immunosuppressive state of high expression of COX7A1, it can better play the role of CD8+ T cells in killing tumor cells." (PMID 38494472, 2024). "Our findings regarding COX7A1 were consistent with recent studies showing that COX7A1 had higher methylation and lower expression in the NSCLC cell line, which suppressed cell viability by downregulating tumor autophagy in vitro." (PMID 39036344, 2024). "Based on co-expression analysis in the TCGA CRC database, COX7A1 was highly co-expressed with LGALS1 coding for galectin-1 (LGALS1/galectin-1), a lectin that is upregulated in the tumor stroma and can inhibit immune response through CD45 protein phosphatase activity (Spearman’s correlation = 0.84)." (PMID 30140386, 2018). "We hypothesize that variation of COX7A1 expression level in different cancer lines could correlate with the magnitude of glycolytic shift or OXPHOS capacity in these lines and consequently with the varying degrees of tumor aggression, invasiveness, and sensitivity to chemotherapeutic regimens." (PMID 29487692, 2018).
cancer (7 papers, 2018 to 2024). A tumor composed of atypical neoplastic, often pleomorphic cells that invade other tissues. "In recent years, some researchers have identified that COX7A1 is implicated in human cancer cell metabolism and therapy." (PMID 31663688, 2019). "Since pre-EFT cell lines and cancer cell lines share many of morphological, proliferative and metabolic features, we reasoned that COX7A1 repression might also be a marker of this hallmark of cancer." (PMID 29487692, 2018). "In recent years, some researchers have found that COX7A1 is related to the metabolism and treatment of human cancer cells." (PMID 38494472, 2024). "Meanwhile, the patients with high COX7A1 expression showed higher probability of cancer invasion, worse clinical efficacy of immunotherapy, worse overall survival (OS) and worse disease-free survival (DFS)." (PMID 38494472, 2024). "Recently, some studies indicated the significant potential of COX7A1 in cancer metabolism and therapy." (PMID 36418320, 2022). "To elucidate the possible mechanism behind COX7A1 suppression in cancer, we analyzed the methylation landscape of the several different cancer cell types that demonstrated downregulation of COX7A1 compared to normal tissues." (PMID 29487692, 2018). "Collectively in all cancer cell lines examined we observed downregulation of COX7A1 expression compared to matching control normal counterparts." (PMID 29487692, 2018). "Cancer cell lines which share many properties with embryonic cells showed a significant reduction in COX7A1 compared to normal cells." (PMID 29487692, 2018). "Extending our analysis of COX7A1 expression to other forms of cancer, we examined cancer cell lines obtained from lung, liver, kidney, breast and skin." (PMID 29487692, 2018). "The results indicated that the overexpression of COX7A1 could inhibit cell proliferation and colony formation ability, as well as promote cancer cell apoptosis." (PMID 31663688, 2019). "COX7A1 could inhibit cell proliferation and colony formation ability, as well as promote cancer cell apoptosis." (PMID 31663688, 2019). "Finally, we extended our analysis to all available cancer cell lines from the highly representative FANTOM5 dataset (over 500 samples) to further test the hypothesis that COX7A1 is generally under-expressed in cancer." (PMID 29487692, 2018). "We therefore conclude that the down-regulation of COX7A1 gene expression may be sufficient to decrease OXPHOS capacity relative to glycolysis correlating with the long-noted trend toward anaerobic glycolysis in embryonic development re-emerging in cancer." (PMID 29487692, 2018). "the embryo-onco phenotype comprising of highly glycolytic/OXPHOS impaired COX7A1 negative cancer cells, iPSCs, embryonic and partially differentiated embryonic derived cell lines and 2)." (PMID 29487692, 2018). "Cancer and embryonic cell lines showed an increased ECAR while the adult-derived preadipocyte cell line showed a statistically significant decreased ECAR that is typical of adult cell lines with upregulated COX7A1 expression." (PMID 29487692, 2018). "Whereas the precise functions of NDUFA3, NDUFA13 (also called GRIM19), COX7A1, COX4I2 and ATP5F1D in oxidative phosphorylation remain somewhat poorly understood, increased expression of NDUFA4L2 is known to drive pro-oncogenic phenotypes in numerous cancer types." (PMID 34782604, 2021). "The level of COX7A1 gene expression was reduced in cancer lines compared to normal cell lines." (PMID 29487692, 2018). "However, suppression of AGO2-1, COX7A1-2, and SLC26A3-1, could also have an opposite effect in NSCLC cells by upregulating the miRs, -25-5p, -30a-3p and -378, which act via MAPK/ERK, and are projected targets of these lncRNAs, and have reduced anti-cancer efficacy when their expression is increased." (PMID 34001990, 2021).
COX7A1 also shares sentences with these, for which no sentence is quoted: adenocarcinoma (1 paper); cardiac hypertrophy (1); cardiomyopathy (1); heart failure (1); Huntington disease (1); lung squamous cell carcinoma (1); osteosarcoma (1); Parkinson disease (1); rhabdomyosarcoma (1); squamous cell carcinoma (1); vascular tumor (1).